FTLP14 (ferritin light chain pseudogene 14)
Gene: Processed pseudogene on chromosome 16 (68,822,587 to 68,823,070, forward strand). Ensembl gene ENSG00000260459.
Diseases named in the same sentence as FTLP14 in open-access papers:
FTLP14 is named in the same sentence as 2 diseases in open-access papers, as found by Europe PMC text mining. Sharing a sentence is not in itself a finding about the gene and the disease.
FTLP14 shares sentences with these, for which no sentence is quoted: ovarian serous cystadenocarcinoma (1 paper); uterine corpus endometrioid carcinoma (1).